TNF (tumor necrosis factor)
Diseases named in the same sentence as TNF in open-access papers (continued):
Sharing a sentence is not in itself a finding about the gene and the disease.
polycystic ovary syndrome (80 papers, 2011 to 2026). A disorder that manifests as multiple cysts on the ovaries. "Spaczynski and colleagues, also demonstrated that TNF-α causes proliferation and differentiation of the theca cells and consequently androgen production and hyperandrogenemia." (PMID 29942935, 2018). "However, imbalanced TNF-α expression is closely associated with polycystic ovary syndrome, diminished ovarian reserve function, ovarian senescence, and granulosa cell apoptosis." (PMID 39568012, 2024). "Moreover, some miRNAs, such as miR-021, miR-27b, miR-103, and miR-155, have been linked to IR and polycystic ovary syndrome (PCOS) indirectly through inflammatory pathways such as tumor necrosis factor (TNF) and interleukin-6 (IL6)." (PMID 37108651, 2023). "It has been reported that follicular atresia, which causes ovarian dysfunction, may be associated with increased TNF-α and other proinflammatory cytokines in rats with experimentally developed polycystic ovary." (PMID 33269158, 2020). "In agreement, a reduction in the endometrial expression of GLUT4 has also been reported in obese patients with polycystic ovary syndrome (PCOS), associated with high levels of TNF-α." (PMID 39997707, 2025). "Studies have indicated that individuals with polycystic ovary syndrome exhibit elevated levels of inflammatory markers such as TNF, IL-6, CRP, IL-18, IL-1β, and white blood cell counts." (PMID 40933264, 2025). "Treatment with BP significantly diminished inflammation and TNF-α levels in polycystic ovary syndrome in mice model." (PMID 38899322, 2024). "Increased plasma concentrations of inflammatory markers, including TNF-α and Interleukin 6 (IL-6), have been shown, for example, in polycystic ovary syndrome." (PMID 37762666, 2023). "Increased levels of the inflammatory cytokines Il-6 (interleukin-6), Il-18 (interleukin-18), TNF-alpha (tumor necrosis factor alpha), hsCRP (high-sensitivity C-reactive protein) and ferritin are present in patients with polycystic ovary syndrome." (PMID 37509592, 2023). "The heterogeneity changed significantly in the strata of polycystic ovary syndrome (I2 = 19%; p = 0.27) and ≥ 3 months (I2 = 10%; p = 0.35) for TNF-α." (PMID 35352233, 2022). "Increase in antibody titers, improved vaccine effects.↓IL-1, TNF-α in polycystic ovary syndrome.↑Neutrophils, IgG, IgA in cancer.High probability of survival in COVID-19." (PMID 34135894, 2021). "Second, hyperandrogenemia can induce a low-grade inflammatory state by increasing the transcripts of the androgen receptor and the release of TNF-α from mononuclear cells, and both contributes to the development of NAFLD." (PMID 29747678, 2018). "This study aimed at investigating the therapeutic effects of curcumin on IL-6, CRP and TNF-α and symptoms of polycystic ovary syndrome." (PMID 29201665, 2017). "The immunohistochemical study of polycystic ovaries treated with curcumin showed a significant decrease in the levels of TNF-α and probably this factor plays an important role in production of cysts and the pathogenesis of polycystic ovary syndrome." (PMID 29201665, 2017). "Having low-grade chronic inflammation such as elevated C-reactive protein (CRP), interleukin-6 (IL-6) and tumor necrosis factor-α (TNF-α) plays a crucial role in polycystic ovary syndrome (PCOS)." (PMID 29201665, 2017). "This study showed that curcumin via inhibition of TNF-α and IL-6, by reducing the follicular sheath, improving ovulation and corpus luteum, will improve histologic features of polycystic ovary and will push it towards having active and healthy ovary." (PMID 29201665, 2017). "Circulating adropin level was negatively correlated with TNF-α level in women with polycystic ovarian syndrome." (PMID 27546995, 2016).
polycystic ovary syndrome (continued). "On the other hand, the expression of TLR4 and TNFα was only affected by hyperandrogenemia." (PMID 39268230, 2024). "Additionally, an increase in the serum levels of IL-6 and TNF-α was observed in polycystic ovary syndrome." (PMID 39495423, 2024). "In another finding, MO leaves could reduce blood glucose, insulin, and TNF-α levels as well as follicle counts in a polycystic ovary syndrome (PCOS) diabetic mice model." (PMID 37570837, 2023). "Moreover, TNF suppresses follicle-stimulating hormone-induced activation of the chorionic gonadotropin receptor promoter, making it a key factor contributing to hyperandrogenemia." (PMID 33623786, 2021). "In polycystic ovary syndrome, hypermethylation in TNF contributes to androgen excess." (PMID 33623786, 2021). "Interestingly, adding anti-TNFα, anti-inflammatory therapy to continuing letrozole treatment largely reversed hyperandrogenemia as well as reproductive and metabolic PCOS-like traits." (PMID 32310267, 2020). "Higher TNF-α has a positive correlation with serum androgen level in overweight and obese adolescents PCOS, it can cause proliferation of theca-interstitial cells in ovaries and consequently hyperandrogenemia." (PMID 31399035, 2019). "Subgroup meta-analysis of TNF-α levels and polycystic ovary syndrome." (PMID 27764100, 2016). "Examples of key terms included “Polycystic Ovary Syndrome”, “PCOS”, “Tumor Necrosis Factor-alpha”, “TNF-α”, and “Inflammation”." (PMID 41561267, 2025). "Regarding chronic low-grade inflammation in polycystic ovary syndrome, most of the articles in the literature have revolved around C-reactive protein, an acute-phase protein produced by the liver in response to interleukin-6 and tumor necrosis factor stimulation." (PMID 38397957, 2024). "Metformin inhibits tumor necrosis factor-alpha (TNF-α) production by pathological B cells in polycystic ovary syndrome (PCOS)." (PMID 35748536, 2022). "High levels of TNF-α play a vital role in the pathogenesis of polycystic ovary syndrome (PCOS) in patients." (PMID 33825169, 2021). "Chronic inflammation is a typical characteristic of polycystic ovary syndrome (PCOS), in which, tumor necrosis factor (TNF)-α plays an important role." (PMID 31170164, 2019). "on polycystic ovary syndrome-induced mice, LC in the dosage of 500 mg/kg for every second day demonstrated a significant reduction in IL-6, MDA, and tumor necrosis factor- α (TNF-α) in the intervention group versus control after 28 days." (PMID 38444016, 2024). "Apigenin treatment reduced the production of the inflammatory cytokines tumor necrosis factor-α (TNF-α) and interleukin-6 (IL-6) in the blood of rats with polycystic ovarian syndrome." (PMID 39457717, 2024). "In mouse models of polycystic ovary syndrome, treatment with DHEA resulted in increased production of cytokines such as serum TNFα, IL-6, IL12p70, and IFNγ." (PMID 37268990, 2023). "In polycystic ovary syndrome, C1QTNF6 upregulates serum levels of proinflammatory factors, such as C-reactive protein (CRP), interleukin 6 (IL-6), and tumor necrosis factor-α (TNF-α)." (PMID 36052307, 2022). "PCOS, polycystic ovary syndrome; 17-OHP, 17-hydroxyprogesterone; FSH, follicle stimulating hormone; LH, luteinizing hormone; TNF-α, tumor necrosis factor-α; IL-6, interleukin-6." (PMID 32187268, 2020). "Evidence relating circulating TNF-α concentrations to polycystic ovary syndrome (PCOS) is heterogeneous and has not been synthesized comprehensively for clinical interpretation." (PMID 41561267, 2025). "Rimonabant treatment for 12 weeks in obese women with polycystic ovarian syndrome resulted in increased circulating levels of VEGF however, the treatment did not alter TNF-α, IL-1β, IL-2, and IL-6, which is in contrast to our results following AM251 treatment." (PMID 36232744, 2022). "TNF-α was also found to differ between women with and without the polycystic ovary syndrome (PCOS)." (PMID 30518097, 2018).
latent infection (79 papers, 2007 to 2026). "Pleural tuberculosis can also be observed in cases of reactivation of a latent infection, and in certain cases, associated with the use of corticosteroid and anti-TNF treatments or presence of comorbidities as HIV/AIDS and diabetes." (PMID 29973541, 2018). "As previously observed, latent infection of control mice with MHV68 was associated with an increase in circulating levels of TNFα, IL-6, IL-12 and IFNγ compared with uninfected mice." (PMID 25599590, 2015). "The major findings from this study are that bioavailability of TNF following anti-TNF therapy is the primary factor for causing reactivation of latent infection and that sTNF—even at very low levels—is essential for control of infection." (PMID 17953477, 2007). "Thus, patients need to be screened for latent infections prior to the initiation of the TNF-α therapy in order to reduce the risk of reactivations." (PMID 37568441, 2023). "Furthermore, by exploiting a low-dose aerosol model of latent infection, a spontaneous and uncontrolled reactivation was observed in TNF-deficient mice, which emphasizes the relevance of TNF in containing M. tuberculosis infection." (PMID 34871095, 2022). "Yet, the use of anti-TNF antibody may be complicated because of the increased risk for reactivation of latent infection." (PMID 31581596, 2019). "TNF blockade compromises host immunity and may increase the risk of reactivation of latent infection resulting in overt pulmonary, pleural and extra-pulmonary tuberculosis." (PMID 29973541, 2018). "TNF is required for host defense mechanisms against mycobacterial infections and the therapeutic blockade of TNF increases the risk of infection and reactivation of a latent infection." (PMID 29973541, 2018). "Regardless of T-cell activation, the study also indicates that IL-6, IL-10, and tumor necrosis factor-alpha levels increase during HCMV latent infection." (PMID 40388758, 2025). "Dutta and colleagues demonstrated that both IFN-γ and TNF-α are essential for resistance to Mtb, and that sustained macrophage activation is critical to prevent reactivation of latent infection." (PMID 41450943, 2025). "While essential for granuloma formation, macrophage activation, and containment of latent infection, TNF can also contribute to tissue damage and immune pathology." (PMID 40427602, 2025). "The bacteria's containment is disturbed, and latent infection is reactivated after TNF-a is inhibited (for example, by the delivery of mAbs)." (PMID 39390211, 2024). "A therapeutic vaccine has certain requirements: it must induce Th1-type cytokines such as IFN-γ and TNF, promote the activation of infected macrophages, and prevent reactivation of latent infection and transmission of pathogens to other people." (PMID 39421744, 2024). "In this study, we sought to identify the major types of cell death in HIV infection and the effects of TNF peptides on latent infection." (PMID 36911666, 2023). "Despite its treatment success, biologic agents, particularly anti-tumor necrosis factor (anti-TNF) drugs, are associated with an increased risk of active infection or reactivation of latent infections." (PMID 36445058, 2023). "It was found by flow cytometry that the specific CD4+T cells of dominant TNF-α+Mtb were different in latent infection and active infection." (PMID 37901241, 2023). "The Chlamydia is characterized by the latent infection of the body and the continuous secretion of cytokines, such as Tumor necrosis factor, interleukin (IL)-1β, and IL-6." (PMID 37660043, 2023). "Here, we use murine gammaherpesvirus 68 (γHV68) to demonstrate that ABCs remain elevated long-term during latent infection and express IFNγ and TNF." (PMID 36477199, 2022). "P. jirovecii is present in a significant portion of the world’s population as latent infections, making them a concern when prescribing TNF inhibitor therapy." (PMID 36159650, 2022).
latent infection (continued). "Protein lysates were prepared from the HIV-1 latently infected T cell line, J-Lat6.3 where the cells were either left untreated (latent infection) or activated with TNF-α (productive infection)." (PMID 34194479, 2021). "This would explain why patients with latent infection have higher levels of TNFα than uninfected contacts." (PMID 32687494, 2020). "The risks of fungal and mycobacterial infections and reactivation of latent infections are increased by TNF-alpha inhibitors." (PMID 31766446, 2019). "The control of latent infection is TNF dependent that requires macrophage and T cells to form and maintain the granuloma structure." (PMID 28280495, 2017). "The reactivation of latent infection is related to the deregulation of specific immune responses, decreasing inflammatory cytokines such as INF-ɣ and TNF-α associated with increasing Th2 cytokines interleukin 4 (IL4) and interleukin 10 (IL10)." (PMID 28934199, 2017). "Once again, we emphasize the necessity of including latent infections in the investigation and differential diagnosis of lesions in patients on treatment with anti-TNFα drugs, mainly in those who live in or travel to endemic areas." (PMID 28934199, 2017). "While HSV hepatitis has not previously been reported in a patient on Infliximab, it is well known that the use of TNFα inhibitors can lead to reactivation of latent infections." (PMID 27818806, 2016). "The proportion of single positive Mtb-specific TNF-α-producing CD4+ T-cells was the strongest predictor of diagnosis of active disease versus latent infection." (PMID 24376464, 2013). "Most of the active TB cases in patients treated with TNF antagonists are due to reactivation of latent infection with Mtb." (PMID 22645622, 2012). "Recently it has been reported that a TNF-alpha+ TB-specific CD4+response can be used to differentiate latent infection from active TB but the sensitivity was just 67%." (PMID 22666453, 2012). "The mechanisms through which TNF mediates control of latent infection is unclear, however studies have reported that administration of TNF inhibitors interferes with TNF mediated phagosome maturation, apoptosis, T cell activation and autophagy." (PMID 22132068, 2011). "In a murine model of gammaherpesvirus (γHV68) infection, latent infection was associated with elevated levels of serum IFN-γ and TNF-α, and protected mice from infection by two distinct bacterial strains." (PMID 17957262, 2007). "The present study takes a theoretical approach toward characterizing the role of TNF in protection against the tubercle bacillus in both active and latent infection." (PMID 17953477, 2007). "The present study takes a computational approach toward characterizing the role of TNF in protection against the tubercle bacillus in both active and latent infection." (PMID 17953477, 2007). "Its latent infection continuously activates the immune system, leading to elevated levels of pro-inflammatory cytokines such as interleukin-6 (IL-6) and tumor necrosis factor-α (TNF-α) in serum, thereby inducing a state of “inflammaging”." (PMID 41312362, 2025). "Here, we noticed that TNF-α is one of the most potent activators of HIV-1 latent infection." (PMID 39692477, 2025). "The results of the linear regression analysis showed that the correlation between IL-2 and TNF-α in the LTBI population was as good as R2 = 0.9655, suggesting a significant positive correlation between IL-2 and TNF-α in the process of immune response to latent infection." (PMID 37112768, 2023). "The high level of IFNγ and TNF cytokine expression indicates that ABCs may be functioning in a unique anti-viral capacity during latent infection." (PMID 36477199, 2022). "During latent infection (35 days and 150 days p.i.), a significantly increased proportion of ABCs continued to express IFNγ and TNF compared to naïve mice, though the proportion of ABCs expressing IFNγ and TNF was decreased compared to acute infection." (PMID 36477199, 2022).
latent infection (continued). "Since higher levels of TNF/IFNγ have been previously reported in T cells of patients with latent infections like CMV26, we hypothesized that this phenomenon is suggestive of antigen-experienced T cell exhaustion, which is concordant with DE genes." (PMID 35411050, 2022). "In particular, anti‐TNF‐α agents, which reduce the production of TNF‐α by macrophages, where mycobacteria survive during LTBI, increase the risk of TB reactivation, mostly resulting from the reactivation of a latent infection." (PMID 35844981, 2020). "In mice, both TNF antibody and its soluble receptor markedly increase mortality in acute Mtb infection, but only the antibody exacerbates chronic infection, which is thought to model human latent infection." (PMID 27242697, 2016). "In addition, a cut-off of 37.4% of single-positive TNF-α+ CD4+ T-cells was calculated as the value allowing the best separation between latent infection and active disease (sensitivity of 100% and specificity of 96%)." (PMID 24376464, 2013). "Histoplasmosis in patients treated with immunomodulatory drugs including anti-TNF therapies may be the result of reactivation of latent infection, or new exposure (or reexposure) of hosts to the organism." (PMID 21605439, 2011). "With the current development of new TNF inhibitor biologics which specifically inhibit solTNF and spare Tm-TNF in the treatment of chronic inflammatory disorders, we investigated the role of Tm-TNF in controlling reactivation of therapeutically induced latent infection." (PMID 22132068, 2011). "We and others have shown that while TNF is critical to control acute infection, it is similarly important to prevent bacilli replication during chronic infection or during drug induced latent infection." (PMID 22132068, 2011). "Regardless of the reasons for these infections, we concur with the conclusion of Theis and Rhodes that, despite screening and efforts to treat latent infections, clinicians need to carefully monitor for the emergence of tuberculosis infections in patients receiving anti-TNF-α therapies." (PMID 20569501, 2010). "The progression from latent infection to active TB disease is the result of an imbalanced rather than a deficient immune response, characterized by a tumor necrosis factor-alpha (TNF-α)-dependent increase in type I IFN production that drives ISR hyperactivation and the necrotization of lung lesions." (PMID 36853048, 2023). "In the HCMV latent infection model, PHA group, T-cell group, and FK506 group exhibited significantly increased interleukin (IL)-6, IL-10, and tumor necrosis factor-alpha secretion." (PMID 40388758, 2025). "In normal to latent infections, we identified eight genes, of which three genes (FZD2, NDUFS8, NLRC4) were up-regulated, and another five genes (CCL4, IL1B, IL1A, TNF, AREG) were down-regulated." (PMID 31749827, 2019). "Most notably and in contrast with latent infection, our subjects with active TB disease had a predominance of CD4+ T cells secreting TNF alone which constituted 46% of the total cytokine response." (PMID 26339657, 2015). "More recently CD4+ T cells producing single tumor necrosis factor (TNF)-α have been suggested to differentiate between active TB and latent infection." (PMID 22523581, 2012). "Analysis of TNF-α, IL-12(p40) and IL-17 in combination following TB10.4 stimulation resulted in over 85% correct classification into active TB disease or latent infection." (PMID 20811496, 2010). "Our experimental findings demonstrate significant upregulation of IL-6, IL-10, and TNF-α in the latent infection model, independent of T-cell activation status." (PMID 40388758, 2025). "For example, infection of M. tuberculosis induced the expression of the human miRNA, miR-889, that suppressed autophagy process via regulation of tumor necrosis factor (TNF)-like weak inducer of apoptosis (TWEAK), which resulted in a latent infection of M. tuberculosis." (PMID 37239318, 2023).